H19 (H19 imprinted maternally expressed transcript)
Diseases named in the same sentence as H19 in open-access papers (continued):
Sharing a sentence is not in itself a finding about the gene and the disease.
tumor (continued). "Thirty days after subcutaneous injection, the tumors formed in H19-siRNA and si-TNFAIP8 groups were substantially smaller than those in the negative control group, as evidenced by a dramatic decrease in tumor volume and tumor weight." (PMID 32514245, 2020). "qPCR confirmed that the relative cycles of Igf2 and H19 significantly decreased in the tumor compared with controls and non-tumor livers." (PMID 32372053, 2020). "Although evidence exists about the tumor suppressor role of H19 in metastatic PCa, the pathophysiological role of H19 in this cancer is not clearly elucidated." (PMID 31426484, 2019). "The tumor suppressor effect of miR-29b-3p was partly reversed by H19 overexpression after co-transfection, and the mRNA level and protein level of MCL-1 were positively correlated with H19." (PMID 30728351, 2019). "Tumor suppressive lncRNAs (GAS5, MEG3, FER1L4 and LINC00672) and oncogenic lncRNAs (CCAT2, BANCR, NEAT1, MALAT1, H19, Linc-RoR, TUG1, TDRG1 and PCGEM1) may be a few such examples." (PMID 30781521, 2019). "As in fetal development, the tumor has continuous metabolic demands and reactivation of the IGF-II/H19 locus could help satisfy these requirements, as it does in early life." (PMID 31590432, 2019). "In relation to miR675, derived from H19, there have been reports of both positive and negative effects on tumor growth, progression, and invasion." (PMID 31590432, 2019). "H19, KCNQ1OT1, and MEG3 are also known imprinted genes that function as tumor suppressors." (PMID 30732658, 2019). "In addition to the IGF2/H19 cluster, possible candidates include those genes from the HOX family and the tumor suppressors." (PMID 31426508, 2019). "Furthermore, H19 and PDK1 levels also displayed a significant correlation in patient tumor samples (n=15)." (PMID 29106390, 2018). "The methylation of H19‐IC remained unchanged (~50%) designating that reprogramming of the imprints have not yet begun in the cell origin of the tumor." (PMID 30003711, 2018). "Among these dysregulated lncRNAs, H19 expression increased with the tumor malignancy grade, whereas expression of Prader Willi/Angelman region RNA 5 (PAR5) and RFPL1 antisense 1 (RFPL1S) decreased with increasing tumor grade." (PMID 28187439, 2017). "Re-expression of H19 in NPC suggests that H19 might be an oncogene, and the down-regulation of H19 in some HNSCC samples implies that H19 might be a tumor suppressor." (PMID 27802187, 2017). "Like H19, 91H is also upregulated in a number of cancers and mirrors studies examining H19’s role as a tumor suppressor and an oncogene with no clear consensus of the overall general mechanism." (PMID 28933364, 2017). "In four different human HCC patient cohorts H19 was distinctly downregulated in tumor tissue compared to normal or non-tumorous adjacent tissue." (PMID 31225433, 2017). "For instance, MALAT-1, HOTAIR, H19, GAS5, UCA1, and GHET1 could regulate the critical pathways of oncogenic and tumor suppression." (PMID 29299179, 2017). "In situ hybridization against H19 revealed low expression of H19 in tumor tissue, but higher expression in the non-tumorous tissue adjacent to the tumor site in an additional patient cohort." (PMID 31225433, 2017). "Recently it was shown that H19 RNA can function as a molecular sponge for let-7 tumor suppressor miRNA, as it harbors both canonical and non-canonical binding sites for the let-7 family of miRNAs." (PMID 26623562, 2016). "Furthermore, we determined that the expression levels of H19 were significantly correlated with the progression of LSCC, including tumor grade, differentiation, neck nodal metastasis, and clinical stage." (PMID 26872375, 2016). "Therefore, abnormal expression of the H19 gene is related to the generation of CRC, and it dually functions as an oncogene and tumor suppressor gene through a variety of mechanisms." (PMID 26637808, 2016).
tumor (continued). "High H19 expression in lung metastasis has also been detected in a limited numbers of human biopsies irrespective of tumor primary origin." (PMID 26623562, 2016). "Moreover, another reports supported that H19-derived miR-675 targeting TGF-β signaling and tumor suppressor RB." (PMID 27716361, 2016). "In addition, many famous lncRNAs have been found to involve in gastric tumorigenesis and progression, such as HOTAIR, H19, MEG3, HOXAAS2 and KRT7-AS, also have functions in another type of tumor." (PMID 27637083, 2016). "Using non-radioactive ISH technique, we found that H19 expression was detected in a high percentage of tumor biopsies with a very high expression in more than 50% of the biopsies." (PMID 26623562, 2016). "With primers specific to H19, we validated our findings by qPCR analysis, and found that H19 levels were significantly higher (5.54-fold) in LSCC tumor tissues than those in adjacent non-neoplastic tissues (3.342 ± 1.436 versus 0.596 ± 0.259) (p < 0.01)." (PMID 26872375, 2016). "H19 is maternally expressed and functions both as a long non-coding RNA involved in tumor suppression and as a trans-regulator of a network of imprinted genes." (PMID 26400872, 2015). "It was further shown that H19 RNA can function as a molecular sponge for let-7 tumor suppressor miRNA, as it harbors both canonical and non-canonical binding sites for the let-7 family of miRNAs." (PMID 25884481, 2015). "The researchers also admit that H19 KO mice do not tend to spontaneously develop tumors, which indicates that H19 is not a tumor suppressor per se but rather its deletion increases cells tendency for cancer." (PMID 26536864, 2015). "The H19 promoter has been proven to be highly active in various tumor types and to show marginal or no activity in the surrounding normal tissue." (PMID 23984081, 2013). "H19 is expressed at substantial levels in several different human tumor types, but only minimally or not at all in normal adult tissues." (PMID 23984081, 2013). "While the H19 gene is not expressed in healthy adult cells, it is expressed in a wide variety of tumor cells of different origins." (PMID 23429271, 2013). "Samples where RFLPs were present in the lymphocyte DNA sample but absent or with an altered ratio in the tumor sample were considered to exhibit LOH in the regions of 8 imprinted genes (H19, IGF2, KCNQ1, LIT1, GTL2, PEG1, PEG3 and NDN)." (PMID 22443985, 2012). "Our previous studies showed that BC-819 treatment was effective in inhibiting the tumor growth compared with the Luc-H19 treated tumors; thus, excluding a nonspecific effect of the BC-819 plasmid and supporting an specific antitumor effect." (PMID 22701803, 2012). "However, an enhanced effect was observed in mice treated with only 25 μg of the double-promoter construct H19-DTA-P4-DTA, wherein tumor development was inhibited by 70% (P = 0.005) compared to the mice treated with the control plasmid H19-Luc-P4-Luc." (PMID 21162716, 2010). "The H19 promoter is known to be differentially activated in various tumor types and to show none or undetectable activity in normal tissue." (PMID 21052499, 2010). "Thus, the simplest explanation for these observations is that there was mono-allelic expression of H19/IGF2 in the normal tissue, which was subsequently lost or allelically switched during tumor development." (PMID 20174472, 2010). "However, an enhanced effect was observed in mice treated with the double-promoter construct H19-DTA-P4-DTA, wherein tumor development was inhibited by nearly 70% (P = 0.005) compared to mice treated with the control plasmid H19-Luc-P4-Luc." (PMID 21162716, 2010). "For one, not every tumor cell of a given type of cancer is positive for expression via the H19 promoter or the IGF2-P4 promoter sequences." (PMID 21162716, 2010). "The LOI positive rate of the LIT1, IGF2 and H19 was higher in patients with advanced tumour stage than with early stage, but the difference was not statistically significant (p = 1.000)." (PMID 19737423, 2009).
tumor (continued). "While most tumor-specific promoters are relatively weak, resulting in insufficient transgene expression levels, the H19 promoter is known to be highly activated in various tumor types and to show no or only marginal activity in the surrounding normal tissue." (PMID 19656414, 2009). "H19 was significantly upregulated in NSCLC (p = 0.008) and in urothelial cancer (p = 0.0013), as calculated by Mann-Whitney U test comparing array-normalized expression in tumor type to all other tumors." (PMID 19305507, 2009). "The epigenetic reactivation of TKTL1, H19, MAGEA2, MAGEA3/6, MAGEA4, MAGEA11, GPR17, GRIN1, and C19ORF28, genes located at diverse chromosomal loci, occurs simultaneously in individual primary tumors from multiple tumor types." (PMID 19305507, 2009). "Results showed that HCC tumors, formed from Hep3B in vitro, transfected with H19 siRNA, encountered a very significant retardation of tumor growth, and in some cases, tumors did not form at all." (PMID 17786216, 2007). "Our observation that knocking down H19 upregulates IGFBP4, which counteracts the tumor promoting activity of IGF2, could provide a link in trans between H19 and IGF2." (PMID 17786216, 2007). "As could be seen in, in some cases with H19 increased expression, the H19 message is abundantly expressed in a human HCC tumor, at a much higher level than the traditional HCC marker α-fetoprotein (AFP)." (PMID 17786216, 2007). "Although three tumours (#33, #34, and #35) were not informative for polymorphisms, these were considered to have undergone LOH because of hypermethylation of H19-pro-DMR and hypomethylation of DMR-LIT1, indicating loss of the maternal chromosomal region." (PMID 16909133, 2006). "Theses effects are accompanied by no change in global tumor DNA methylation evaluated by two methods, and lack of demethylation in the imprinted gene H19 and the "normally methylated" 1.2 clone in peripheral mononuclear blood cells." (PMID 15862127, 2005). "In Wilms tumors, loss of imprinting leads to biallelic expression of IGF2 and reciprocal loss of expression of H19, a non-transcribed RNA with tumor suppressor activities, while IGF2 promotes tumor formation by inhibiting apoptosis." (PMID 16248899, 2005). "Alternatively, given that H19 is regulated by broader oncogenic pathways and tumor microenvironmental factors rather than anatomical site alone, its expression may not significantly differ between tumor sites." (PMID 41521159, 2026). "The presence of H19 in tumor tissues or body fluids could serve as a non-invasive diagnostic biomarker for early detection or monitoring of disease progression." (PMID 41361062, 2025). "Additionally, they play critical roles in reprogramming the tumor immune microenvironment (TIME), influencing T cell trafficking (H19), MDSC differentiation (PVT1, RUNXOR, Lnc57Rik), Treg-mediated immunosuppression (SNHG16), and promoting immune cell-cancer cell interactions (LNMAT1, JHDM1D-AS1)." (PMID 40527978, 2025). "Therefore, H19 up- and downregulation may contribute to immune cell infiltration in the TME of PTC in a varied, and tumor-specific manner." (PMID 38785786, 2024). "However, the presence of LncRNA H19 SNP rs2107425 on the tumor T status is significant even in the enrolled study population with different EGFR phenotype, which implies the influence of LncRNA H19 SNP rs2107425 on LADC disease course cannot be overlooked especially for those with EGFR wild-type." (PMID 33799753, 2021). "In an established nude mouse xenograft model using T3M4, PANC-1, COLO357 and CAPAN-1 cells with a siH19 mixture or lenti-H19-GFP, H19 overexpression could increase tumor volume and weight and promote tumor growth quickly, while H19 knockout exerted the opposite consequence." (PMID 34977037, 2021).
tumor (continued). "Of note, no MEG3 downregulation or H19 upregulation was observed in tumor lesions." (PMID 33030666, 2021). "H19 facilitates the invasion of colon cancer cells via miR-200a sponging mechanism and consequential ZEB1/2 upregulation, while its overexpression results in upregulation of vimentin and downregulation of E-cadherin, and indicates a significant increase in tumor size in vivo." (PMID 35011635, 2021). "In pre-experiment, NC shRNA or H19 shRNA alone did not significantly affect tumor (Data no shown)." (PMID 32345117, 2020). "Evidence of numerous human tumors displaying either overexpression or lack of expression of H19 suggests the possibility of context-dependent oncogenic and tumor-suppresive roles." (PMID 33519915, 2020). "However, H19 silencing decreased ER-beta expression and reduced tumor progression in PTC stem cells indicating the fact that ER-beta and H19 down regulation via E2 could be used as a therapeutic approach to reduce tumor progression in PTC." (PMID 32102500, 2020). "Additionally, H19 may be a direct transcriptional target of and is induced by MYC in NSCLC tumor tissues." (PMID 32438606, 2020). "Here, the authors found that H19 functioned as a promoter of differentiation during the embryonic period and that absence of H19 at this stage could leave cells vulnerable to forming cancer, thereby seemingly acting as a tumor suppressor." (PMID 31616462, 2019). "On the contrary, under combined stimuli, H19 level is transcriptionally reduced, and CDH1 and β integrin expression released, switching tumor dissemination toward an alternative mechanism, the cohesive phenotype, suggesting a tumor suppressor role for H19 in this condition." (PMID 31426484, 2019). "We also observed a moderate positive association between expression levels of oncogenic miR-675 and H19, as well as a moderate negative correlation between H19 and miR-133 family members and other tumor suppressive microRNAs like miR-486-5p, miR-182-5p or miR-203a-3p." (PMID 30557328, 2018). "Importantly, we uncover a function of H19, which controls cell/tumour growth through inhibiting function of mTORC1 but not mTORC2." (PMID 30397197, 2018). "Interestingly, we found that H19 overexpression led to pronounced inhibition of 4E-BP1 phosphorylation as expected, but CAB treatment had less effect on 4E-BP phosphorylation in the xenograft tumours of GH3 cells." (PMID 30397197, 2018). "As expected after the discovery of the first lncRNAs in cancer like H19, MALAT1, PCA3, the list of lncRNAs involved in tumor progression and metastasis is growing and their role as prognostic biomarkers and as prominent therapeutic targets in tumor patients is becoming increasingly more evident." (PMID 30018188, 2018). "The H19 gene is highly expressed in common metastatic sites regardless of tumor primary origin." (PMID 28793797, 2018). "Although detailed biological function of the association between H19 and ISM1 has not been illustrated, it has been proposed that this association regulates GC cell growth and mobility because ISM1 regulates surviving and apoptosis in many tumor cells." (PMID 28230721, 2017). "For instance, hypermethylation at the ICR of the H19/Igf2 domain can potentially result in complete repression of H19 and bi-allelic expression of Igf2, a known oncogene, whereas hypermethylation at the ICR of the Peg3 domain can potentially result in repression of Peg3, a putative tumor suppressor." (PMID 28855972, 2017). "Examples of lncRNAs (H19, HOTAIR, ANRIL, MIR31HG), that recruit chromatin modifying activities and have been shown to have roles in cellular growth control and carcinogenesis, or are known to regulate the expression of tumour-suppressor genes, are presented below." (PMID 28587163, 2017). "Thus it was deduced that H19 contributes to MET and to the suppression of tumor metastasis." (PMID 26623562, 2016).
tumor (continued). "In subgroups analysis, we found that the levels of H19 were significantly related to the histological grade (OR = 0.50, 95% CI = 0.29–0.86, P = 0.01), TNM stage (OR = 0.19, 95% CI = 0.11–0.33, P < 0.01), and tumor invasion depth (OR = 0.11, 95% CI = 0.04–0.27, P < 0.01) in GC." (PMID 27672656, 2016). "The growing evidences have indicated that H19 involved in both proliferation and differentiation processes, together with epithelial to mesenchymal transition (EMT) and also mesenchymal to epithelial transition (MET), suggesting its contribution in tumor both initiation and progression." (PMID 27809873, 2016). "Simultaneous knockdown of H19 and inhibited miR-342-3p had no impact on tumor formation." (PMID 27716361, 2016). "In spite of the strong supportive evidence for H19 and miR-675 involvement in EMT, which is regarded as a de-differentiation/trans-differentiation process, there is enough contradictory data to position H19 as a tumor suppressor and a pro-differentiation factor." (PMID 26536864, 2015). "Indeed, the sensitivity of plasma H19 for dysplasia detection was much higher than that of conventional tumor markers, including CEA and CA199 at our institute (data not shown)." (PMID 26096073, 2015). "Due to possible extracellular signaling shift in the secondary site to which the tumor cell has intravasated, H19 may support MET, colonization and proliferation, processes in which H19 was already involved at the very initial stages of tumor formation at the primary site." (PMID 26536864, 2015). "However, H19 was expressed relatively higher in nontumor tissues compared to those in tumor tissues of HCC patients (P < 0.001)." (PMID 26136615, 2015). "There was a prominent gender disparity in the H19 expression in tumor versus non-tumor liver: in females, it was similar in the post-PHx tumors, while it significantly decreased in spontaneous tumors, whereas in males, it was significantly increased in both spontaneous and post-PHx groups." (PMID 25401338, 2014). "However, several lines of evidence suggest that H19 is more likely an oncogene, rather than a tumor suppressor." (PMID 23965803, 2013). "Interesting, H19 expression is not increased in every types of tumor." (PMID 24063685, 2013). "The full role of H19 has not yet been delineated, but it is thought to function as a tumour-suppressor, and may negatively regulate cellular proliferation." (PMID 22511876, 2012). "Interestingly, we recently discovered in human that an antisense H19 transcript, named the 91H RNA (or H19os for “H19 opposite strand” transcript), augments in trans the paternal IGF2 expression which is known to favour tumour progression." (PMID 22662250, 2012). "Accordingly, destruction of the H19 and IGF2 expressing tumor cells not only will eliminate part of the tumor but will also diminish the supply of mitogenic IGF2 to neighboring tumor and non-tumor cells and may lead to arrest of tumor growth and prevent following metastases process." (PMID 21162716, 2010). "Although no H19 expression was detected in the ES-2 cell line, (line 6), significant H19 RNA was detected in all the developed tumors examined, supporting the role of H19 in tumor growth." (PMID 19656414, 2009). "Equally, because there was no tumor development in these mice, the true role of H19 could not be properly evaluated." (PMID 19956719, 2009). "Furthermore, in one of the experiments, in the four mice receiving Hep3B transfected with the siRNA-3 targeting the H19 message, we did not detect even a trace of tumor as opposed to the five receiving Hep3B transfected with luc siRNA." (PMID 17786216, 2007). "In addition H19 RNA may suppress IGF2 expression in trans and has tumour suppressor functions in cell transfection studies." (PMID 15885138, 2005).